VDR (vitamin D receptor)
Diseases named in the same sentence as VDR in open-access papers (continued):
Sharing a sentence is not in itself a finding about the gene and the disease.
tumor (continued). "Moreover, anti‐tumour activity of the biologically active form of vitamin D, 1,25‐dihydroxyvitamin D3 (1,25‐(OH)2D3) acting via the vitamin D receptor (VDR), has been verified in human and rat prostatic tissue." (PMID 34015193, 2021). "A significantly increased expression of VDR was observed in tumor cells of OSCC." (PMID 34821593, 2021). "IRX4 has been described as a tumor suppressor in PCa with the interaction of vitamin D receptor." (PMID 33919200, 2021). "Nuclear expression of VDR was examined by immunohistochemistry in tumor tissue and in the lungs." (PMID 33172201, 2020). "In addition, knockdown of the vitamin D receptor (VDR) abolished the radiosensitization of 1α,25(OH)2D3, which confirmed that 1α,25(OH)2D3 radiosensitized tumor cells that depend on VDR." (PMID 32848720, 2020). "The VDR and RORγ showed both a nuclear and a cytoplasmic location, and their expression levels were found to be reduced in the primary and metastatic OCs in comparison to normal ovarian epithelium, as well as correlated to the tumor grade." (PMID 33227893, 2020). "VDR is present mainly in metabolic tissues, but also in almost all human cell types; furthermore, VDR expression is low in normal cells, increases in malignant cells and is reduced with tumor growth." (PMID 33133014, 2020). "Additionally, we also report quantity of FOXP3 expressing lymphocytes in tumor microenvironment and its correlation with VDR expression." (PMID 32513132, 2020). "Recent literature shows anti-tumor property of vitamin D and these effects are mediated by VDR." (PMID 32513132, 2020). "The molecular mechanism of this phenomenon may be related to the change in the expression levels of VD receptor (VDR) in tumor tissues." (PMID 33817215, 2020). "The active form of vitamin D exerts its effects through interaction with its cognate intracellular nuclear receptor, the vitamin D receptor (VDR), which subsequently activates a number of genes involved in immune cell proliferation, oncogenesis, and tumour suppression." (PMID 32626760, 2020). "In addition, expression of VDR was significantly decreased in tumor tissues obtained from male patients compared with their matched ANCTs (ER = 0.31, P value = 0.02)." (PMID 32514489, 2020). "Nuclear VDR immunostaining correlated negatively with expression of the proliferation marker Ki-67, but this correlation was limited to the central part of the tumor (r = −0.28, p = 0.035), defined as the older part of the tumor, with no signs of dynamic growth." (PMID 33227893, 2020). "VDR is a key participant of the Wnt/β-catenin pathway in controlling tumor growth in CRC." (PMID 33145139, 2020). "The acidic environment would change the cellular proteome and cellular metabolism to a large scope; we discovered that VDR could attenuate the acidic tumor microenvironment-mediated promotion of CSC phenotype." (PMID 32900990, 2020). "Antiproliferative effects of 1α,25(OH)2D3 may involve the mechanisms associated with apoptotic pathway activation and angiogenesis inhibition, and the vitamin D receptor was proposed to be crucial for tumor suppression." (PMID 32245092, 2020). "Our results suggest that VDR signalling dampens the adaptive immune system, which may jeopardize the anti-tumour immunity of the patient and, hence, could potentially counteract the effect of immunotherapies." (PMID 33060625, 2020). "In addition, progesterone enhanced the anti-tumor activities of VD3 by upregulating of VDR expression in endometrial cancer cells." (PMID 30961641, 2019). "Furthermore, compelling evidence was provided for the tumor suppressor function of VDR and agonists in breast tissue." (PMID 31731733, 2019). "Notably, the expression level of VDR showed progressive increase during T cell differentiation from naïve to tumor-reactive subtype." (PMID 31892342, 2019).
tumor (continued). "In the present material, VDR was found almost exclusively in tumor cells." (PMID 31358030, 2019). "Transcription factor binding motif enrichment analysis identifies several immune-related transcription factors, including three exhaustion-related genes (NR4A1, BATF, and EGR2) and VDR, which potentially play an important regulatory role in tumor-reactive CD8+ T cells." (PMID 31892342, 2019). "This endeavor warrants the scrutinization of the central role of the VDR in 1α,25(OH)2D3 action and the therapeutic roles of 1α,25(OH)2D3 and its analogs in maintaining gastric tissue homeostasis and controlling tumor proliferation, and thereby in the betterment of human health." (PMID 31387330, 2019). "Vitamin D receptor (VDR) is a membrane receptor for vitamin D. However, whether VDR is a tumour suppressor or an oncogene remains unclear." (PMID 31819048, 2019). "The VDR is also considered as a tumor suppressor in the skin." (PMID 30321335, 2019). "It is unclear whether the tumor suppressive effect of 1α,25(OH)2VD3 and 9-cis-retinoic acid is mediated through telomerase inhibition since VDR-RXR can affect diverse growth-regulatory signaling pathways." (PMID 29415465, 2018). "Taken together, our data demonstrated that VDR could act as a tumour suppressor to suppress proliferation, migration and invasion in RCC cell lines." (PMID 29659618, 2018). "Indeed, a cell-line study has demonstrated that VDR activation regulates apoptosis and cell differentiation, and suppresses tumour proliferation." (PMID 30344947, 2018). "Taken together, our findings confirmed that VDR functions as a tumour suppressor in RCC cell lines." (PMID 29659618, 2018). "Whether this is a tumour promoting effect or compensatory response to facilitate VDR anti-proliferative activity is currently unknown." (PMID 29659559, 2018). "Our findings in the sensitivity analysis may therefore arise due to a difference in VDR expression between tumour sites." (PMID 30344947, 2018). "Only VDR expression was significantly upregulated in CRPC compared to primary tumours." (PMID 30627063, 2018). "Patients with no VDR expression had a 2-fold higher increased risk of death than in patients whose tumours expressed VDR (HR 2.00 95% CI 1.07–3.76)." (PMID 30344947, 2018). "Recent findings support the role of VDR as a tumor suppressor in the skin." (PMID 29998107, 2018). "Limited research is available to explore the impact of neoadjuvant treatment upon VDR expression of the primary tumour, although one small study in 15 patients found those with higher VDR expression were less likely to respond to treatment, indicating a potential interaction." (PMID 30344947, 2018). "Censored survival analysis was performed to evaluate whether tumors in mice with high levels of LSD1 or VDR grew faster than those in mice with low levels of LSD1 or VDR, measured as time for the tumor to reach 1000 m3 from the time of pellet removal." (PMID 28811844, 2017). "The results shown in the present study suggest that also VDR overexpression could contribute to the impaired myogenesis observed in tumor hosts, mainly by altering the expression of myogenic factors involved in the differentiation program, such as myogenin." (PMID 28423519, 2017). "One reason for the apparent impairment in tumor development with VDR-KD cells could be that the time required for inoculated cells to commence rapid proliferation and form tumours in VDR-KD cells is longer than that for the control cells." (PMID 28460457, 2017). "In this regard, ERK activation occurring in the skeletal muscle of cachectic tumor-bearing animals could be responsible for the establishment of a ‘VDR-prone’ environment, resulting in enhanced VDR-dependent signaling." (PMID 28423519, 2017). "The antineoplastic effect of 1,25(OH)2D3 requires the expression of VDR in tumor cells." (PMID 28489590, 2017).
tumor (continued). "Moreover, vitamin D receptor (VDR) activation reverts caPSCs activation, resulting in reduced inflammation and fibrosis, inhibition of tumor growth, and increased survival in preclinical models." (PMID 29211796, 2017). "Of note, VDR expression also negatively correlate with tumor progression: relatively high VDR concentrations are found in non-malignant hyperplastic tissue while progression to malignant growth is often associated with a reduction or complete loss of VDR expression." (PMID 28460457, 2017). "Expression of LSD1 and VDR (IHC) were correlated with tumor growth using log-rank test." (PMID 28811844, 2017). "VDR knockdown significantly reduced tumor growth compared to MCF-7-NT cells." (PMID 28460457, 2017). "An interaction of vitamin D and VDR can induce a cascade of gene regulation and cell signaling to play important roles in their anti-tumor mechanisms, such as suppression of proliferation, stimulation of apoptosis and autophagy, inhibition of angiogenesis, regulation of immune system and so on." (PMID 28206978, 2017). "Other studies showed that the VDR ligand and all-trans retinoic acid (ATRA) can act through VDR or Wnt-β-Catenin signaling pathway to reprogram PSC to the quiescent state to reduce the fibrotic content in tumor interstitium, which is promising for the second-wave nanomedicine therapy." (PMID 29311946, 2017). "Therefore, it would be very helpful to compare the VDR expression of CTCs with that of the corresponding primary tumor." (PMID 28632174, 2017). "Vitamin D supplementation is such a potential adjuvant treatment strategy, since vitamin D may protect against tumor progression through its pleiotropic anticancer effects via binding to its Vitamin D Receptor (VDR)." (PMID 28835228, 2017). "The potential anti-tumor mechanisms of vitamin D may be relevant to its specific receptor, vitamin D receptor (VDR)." (PMID 28206978, 2017). "On this line, VDR up-regulation in the skeletal muscle of tumor hosts could be considered per se as a condition sufficient for its transcriptional activity." (PMID 28423519, 2017). "Thus, we next examined the expression of VDR in tumor differentiated cells versus normal counterparts." (PMID 27275819, 2016). "VDR acts as a master transcriptional regulator of PSCs to reprise the quiescent state, resulting in induced stromal remodeling, increased intratumoral gemcitabine, reduced tumor volume, and a 57% increase in survival compared to chemotherapy alone." (PMID 27655706, 2016). "In addition,tumor Vitamin D receptor (VDR) mRNA levels, as measured by qRT-PCR, were notsignificantly associated with tumor PTH immunoreactivity or PTH mRNAintensity." (PMID 26865585, 2016). "Finally, VDR was identified as a tumor suppressor in the skin, with three predominant mechanisms underlying its function: inhibition of proliferation and induction of dedifferentiation, immune control and involvement in DNA damage response (DDR)." (PMID 27058533, 2016). "Thus, we became interested in the interacting roles of HH and β-catenin signaling in tumor suppression by VDR, a subject to which I will return." (PMID 27462278, 2016). "No doubt other pathways will emerge that contribute to a greater or lesser degree to the predisposition of the epidermis lacking VDR and/or Casr to tumor formation." (PMID 27462278, 2016). "Studies that investigate in depth the functional relationship between BRCA1 and the vitamin D/VDR axis could lead to important discoveries about the role of these tumor suppressor pathways in a variety of aging-related diseases." (PMID 27145372, 2016). "These interactions represent points of convergence between VDR and canonical Wnt signaling in CRC, which has been linked to inhibition of Wnt signaling, tumor growth inhibition, the activation of apoptotic pathways, inhibition of angiogenesis and inhibition of tumor-promoting inflammation." (PMID 27092172, 2016).
tumor (continued). "A study published in May 2015 found that activation of vitamin D/VDR signaling led to inhibition of FOXM1, a direct transcriptional target of VDR, causing a suppression of tumor stemness, growth, and metastasis." (PMID 26867933, 2016). "However, we did find that levels of the β-catenin target gene cyclin D1 were significantly augmented in normal epithelial and tumor cells upon VDR ablation." (PMID 27768599, 2016). "In order to analyze whether the two VDR SNPs affect tumor progression, BsmI and FokI genotypes were correlated with histopathological tumor characteristics." (PMID 26517870, 2015). "This can be explained as many cytokines and inflammatory peptides excreted by tumour-infiltrating leucocytes as well as tumour cells may influence VDR expression." (PMID 25662556, 2015). "Similarly, MMTV-Ron VDR−/− mice exhibited significantly shorter tumor latency than VDR heterozygous and homozygous littermates." (PMID 26008979, 2015). "However, MMTV-Ron mice homozygous or heterozygous for VDR exhibited significantly longer times to palpable tumor formation compared to VDR−/− mice." (PMID 26008979, 2015). "Additionally, we analyzed VDR immunostaining in relation to prognostic factors such as tumor advancement, mitotic activity and most importantly we related the findings to the overall survival time." (PMID 26501255, 2015). "Nuclear receptors have also been noted as having tumor suppressive functions including VDR’s protective function in colon cancer; PPARg’s activation in reducing tumorigenicity in many cancer tissue types; TR4 and RARb as tumor suppressors in prostate, and NUR77 and NOR1 as tumor suppressors in AML." (PMID 26217306, 2015). "Finally, CYP24A1 expression in tumor tissue was correlated with VDR mRNA levels (rs=0.57, P<0.05; Spearman's test)." (PMID 26260259, 2015). "Furthermore, altered VDR expression was observed in in tumor-adjacent hyperplastic/dysplastic oral epithelium, where VDR immunostaining was observed throughout the entire thickness of the epithelium." (PMID 24626468, 2014). "To determine whether there is a correlation between VDR expression, Vitamin D3 diet, and tumor grade, we determined VDR intensity in tumors of each grade from mice fed increasing doses of dietary Vitamin D3." (PMID 25191969, 2014). "Given the effects of VDR on limiting cell proliferation, as well as its putative tumor-suppressor role in the skin, as demonstrated by animal studies, this increased VDR expression in the neoplasms seems paradoxical." (PMID 24626468, 2014). "In this study, we sought to delineate whether dietary Vitamin D3 offered any protection against UVB induced tumor formation and whether it preferentially induced expression of ΔNp63α, VDR, or PTEN in vivo." (PMID 25191969, 2014). "However, this correlation is lost in PDAC patients where VDR protein levels are highest in the endocrine cells while the CYP24A1 is highest in tumor cells." (PMID 25090635, 2014). "Our results suggest that increased dietary Vitamin D3 may enhance UVB induced tumor formation and progression by decreasing the expression of VDR in the epidermis while increasing ΔNp63α." (PMID 25191969, 2014). "Since most of the anti-carcinogenic effects of vitamin D seem to be mediated by the vitamin D receptor (VDR), individual- or tumor-specific differences in VDR may be of importance." (PMID 24952509, 2014). "However, the role of VDR in individual cell types (i.e., epithelial, adipose, fibroblast, endothelial, immune) of normal and tumor tissues remains to be clarified." (PMID 24982636, 2014).
tumor (continued). "Taken together, these studies suggest that increased dietary Vitamin D3 may enhance UVB induced tumor formation and progression, at least at supra-physiologic doses, by decreasing the expression of VDR while increasing the ΔNp63α to PTEN ratio." (PMID 25191969, 2014). "Furthermore, the mechanisms by which VDR integrates signaling between diverse cell types and controls soluble signals and paracrine pathways in the tissue/tumor microenvironment remain to be defined." (PMID 24982636, 2014). "It has been proven that VDR expression positively correlates with tumour suppression." (PMID 24086705, 2013). "Furthermore, our results suggested that induction of VDR, Cyp24, Cyp27B1 and hCAP18/LL-37 requires macrophageTLR2/6 activity in tumor microenvironments." (PMID 23424670, 2013). "Third, VDR regulates the expression of oncogenic and tumor suppressing lncRNAs in keratinocytes." (PMID 24202452, 2013). "Other studies indicate that the VDR acts as a tumour suppressor independently of 1,25(OH)2D3." (PMID 23049920, 2012). "This study provides insight into the molecular mechanisms involved in astemizole-calcitriol combined antineoplastic effect, offering scientific support to test both compounds in combination in further preclinical and clinical studies of neoplasms expressing VDR and Eag1." (PMID 22984610, 2012). "Overall, the sample size is not large enough to detect significant differences of minor VDR polymorphisms or synergistic effects of the gene-environment and stratification by tumor stage or primary site." (PMID 22242137, 2011). "Therefore, the expression of many tumor suppressors such as VDR was much lower (FC = 0.3010) compared with group FA2 and FA3, which was opposite to oncogenes." (PMID 22206623, 2011). "Similarly, enlarged blood vessels and increased vessel volume in TRAMP-2 tumors were found in the VDR knockout mice, suggesting that antitumor angiogenesis was directly affected through VDR and calcitriol at tumor sites." (PMID 21991434, 2011). "Thus, during mammary malignant transformation, tumour cells lose their ability to synthesize the active form of Vitamin D and respond to VDR-mediated Vitamin D effects, while increasing their ability to degrade this hormone." (PMID 20831823, 2010). "VDR is essential for regulation of calcium homeostasis by 1,25D, but its role in the anti-tumor effects mediated by vitamin D signaling remains unclear." (PMID 19863778, 2009). "Additionally, clinical and tumour phenotypic variables have been taken into account to better define the involvement of VDR in these pathologies." (PMID 19105801, 2008). "This suggests that the VDR expression observed in low-grade tumours and the tumour-localised production of this hormone could be an autocrine/paracrine means to control tumour progression." (PMID 15770204, 2005). "If upregulation of SNAIL or downregulation of VDR in tumours could be monitored by RT–PCR analysis of circulating RNA levels, this would constitute a valuable tool for the selection of candidates for therapy with vitamin D analogues." (PMID 15770204, 2005). "VDR is expressed in most tumors, and numerous studies suggest that higher VDR expression correlates with better prognosis and longer overall survival, whereas reduced or absent VDR expression is associated with tumor progression and poorer outcomes." (PMID 41282147, 2025). "Additionally, tacalcitol increased VDR expression in young 67NR and aged 4T1 tumor-bearing mice." (PMID 40894304, 2025). "Our results showed that high VDR expression was positively correlated with a high Gleason score (P < 0.001), poorer prognostic International Society of Urological Pathology grade groups (P < 0.001), advanced tumor stage (P = 0.01), and poorer response to androgen deprivation therapy (ADT)." (PMID 39963174, 2025).